PCDHB3 (protocadherin beta 3)
Description:
Potential calcium-dependent cell-adhesion protein. May be involved in the establishment and maintenance of specific neuronal connections in the brain.
Synonyms: PCDH-BETA3
Tractability: Antibody: its Gene Ontology location is reachable by antibodies, with high confidence; UniProt places it where antibodies can reach, with medium confidence; UniProt predicts a signal peptide or a membrane-spanning region. PROTAC: ubiquitination databases record sites on it.
Gene: Protein-coding gene on chromosome 5 (141,100,473 to 141,103,827, forward strand). Ensembl gene ENSG00000113205.
Subcellular location: Cell membrane
Subcellular location (Human Protein Atlas): Vesicles
Gene Ontology:
Molecular function: protein binding; cell adhesion molecule binding; calcium ion binding
Biological process: calcium-dependent cell-cell adhesion; cell adhesion; chemical synaptic transmission; nervous system development; synapse assembly; homophilic cell-cell adhesion
Cellular component: membrane; plasma membrane; synapse
Genetic constraint (gnomAD): Loss-of-function variants: 0 observed, 0.13 expected, observed/expected ratio (o/e) 0, 90% interval 0 to 1.89. That is too few expected variants to judge how well the gene tolerates losing a copy. Missense variants: 966 observed, 1,031.7 expected, observed/expected ratio (o/e) 0.94, 90% interval 0.89 to 0.99. Synonymous variants: 479 observed, 467.73 expected, observed/expected ratio (o/e) 1.02, 90% interval 0.95 to 1.1.
Homologues: Orthologues: macaque PCDHB3 (97% identical), mouse Pcdhb3 (78% identical), rat Pcdhb3 (78% identical). Paralogues in human: PCDHB2 (80% identical), PCDHB6 (77% identical), PCDHB15 (77% identical), PCDHB14 (76% identical), PCDHB13 (76% identical), PCDHB16 (76% identical), PCDHB5 (76% identical), PCDHB4 (75% identical), PCDHB11 (75% identical), PCDHB8 (75% identical), PCDHB10 (75% identical), PCDHB7 (75% identical), and 49 more.
Diseases named in the same sentence as PCDHB3 in open-access papers:
PCDHB3 is named in the same sentence as 7 diseases in open-access papers, as found by Europe PMC text mining. Sharing a sentence is not in itself a finding about the gene and the disease. The quoted sentences say what the papers report.
colorectal cancer (1 paper, 2022). A primary or metastatic malignant neoplasm that affects the colon or rectum. "Although the role of protocadherin beta 3 (PCDHB3) has not been fully explored in male infertility, studies have shown their tumour-suppressive properties, however, as they inhibit colorectal cancer cell proliferation, migration and epithelial to mesenchymal transition." (PMID 35207567, 2022).
diabetes (1 paper, 2022). "There were 8 differentially methylated genes (CDH2/PCDHB10/PCDHB11/PCDHB14/PCDHB16/PCDHB3/PCDHB6/PCDHB9) in the LAA subgroup and 1 (CDH2) in the SVD subgroup after adjusting for smoking, drinking, history of hypertension and diabetes, and blood lipid levels (p < 0.05)." (PMID 35480311, 2022).
gastric cancer (1 paper, 2023). A primary or metastatic malignant neoplasm involving the stomach. "Moreover, overexpression or depletion of PCDHGA9 induced a decrease or increase, respectively, in the migration and invasion of gastric cancer cells, and PCDHB3 inhibited the migration of CRC cells." (PMID 37748077, 2023).
male infertility (1 paper, 2022). The inability of the male to effect fertilization of an ovum after a specified period of unprotected intercourse. "This section will briefly highlight the role of the eight (TNP1, TNP2, PDHA2, LDHC, SPINK2, ODF1, ODF2, and PCDHB3) common DEGs in male infertility as obtained from our findings." (PMID 35207567, 2022).
tumour (2 papers, 2009 to 2022). "These include PCDHGA3, hypermethylated in 24/27 tumours (89%), PCDHGB4 (23/25, 92%), PCDHGA2 (11/13, 85%) and PCDHB3 (21/33, 64%)." (PMID 19956686, 2009).
PCDHB3 also shares sentences with these, for which no sentence is quoted: hearing loss (1 paper); Hypertension (1).